LIMD1 (LIM domain containing 1)
Description:
Adapter or scaffold protein which participates in the assembly of numerous protein complexes and is involved in several cellular processes such as cell fate determination, cytoskeletal organization, repression of gene transcription, cell-cell adhesion, cell differentiation, proliferation and migration. Positively regulates microRNA (miRNA)-mediated gene silencing and is essential for P-body formation and integrity. Acts as a hypoxic regulator by bridging an association between the prolyl hydroxylases and VHL enabling efficient degradation of HIF1A. Acts as a transcriptional corepressor for SNAI1- and SNAI2/SLUG-dependent repression of E-cadherin transcription. Negatively regulates the Hippo signaling pathway and antagonizes phosphorylation of YAP1. Inhibits E2F-mediated transcription, and suppresses the expression of the majority of genes with E2F1-responsive elements. Regulates osteoblast development, function, differentiation and stress osteoclastogenesis. Enhances the ability of TRAF6 to activate adapter protein complex 1 (AP-1) and negatively regulates the canonical Wnt receptor signaling pathway in osteoblasts. May act as a tumor suppressor by inhibiting cell proliferation.
Tractability: Antibody: its Gene Ontology location is reachable by antibodies, with high confidence. PROTAC: ubiquitination databases record sites on it; its protein half-life has been measured.
Gene: Protein-coding gene on chromosome 3 (45,555,394 to 45,686,341, forward strand). Ensembl gene ENSG00000144791.
Subcellular location: Cytoplasm; Nucleus; Cytoplasm, P-body; Cell junction, adherens junction; Cell junction, focal adhesion
Subcellular location (Human Protein Atlas): Focal adhesion sites; Nucleoplasm
Pathways (Reactome):
Cellular responses to stimuli: Oxygen-dependent proline hydroxylation of Hypoxia-inducible Factor Alpha
Gene Ontology:
Molecular function: protein binding; transcription corepressor activity
Biological process: miRNA-mediated gene silencing by inhibition of translation; miRNA-mediated post-transcriptional gene silencing; negative regulation of DNA-templated transcription; negative regulation of hippo signaling; P-body assembly; phosphorylation; response to hypoxia; cytoskeleton organization; negative regulation of canonical Wnt signaling pathway; negative regulation of osteoblast differentiation; osteoblast development; regulation of DNA-templated transcription
Cellular component: adherens junction; cytoplasm; focal adhesion; nucleoplasm; nucleus; P-body; RISC complex; cytosol; transcription regulator complex
Genetic constraint (gnomAD): Loss-of-function variants: 20 observed, 55.72 expected, observed/expected ratio (o/e) 0.36, 90% interval 0.25 to 0.52. The upper end of that interval is the gene's LOEUF score, 0.52, which puts it in group 2 of 6, group 1 being the genes least tolerant of losing a copy. Missense variants: 817 observed, 863.11 expected, observed/expected ratio (o/e) 0.95, 90% interval 0.89 to 1. Synonymous variants: 330 observed, 353.99 expected, observed/expected ratio (o/e) 0.93, 90% interval 0.85 to 1.02.
Homologues: Orthologues: chimpanzee LIMD1 (99% identical), macaque LIMD1 (97% identical), pig LIMD1 (86% identical), dog LIMD1 (79% identical), mouse Limd1 (77% identical), rat Limd1 (77% identical), guinea pig LIMD1 (74% identical), rabbit LIMD1 (70% identical), tropical clawed frog sec61b (41% identical), zebrafish limd1a (15% identical). Paralogues in human: WTIP (28% identical), AJUBA (26% identical).
Diseases named in the same sentence as LIMD1 in open-access papers:
LIMD1 is named in the same sentence as 49 diseases in open-access papers, as found by Europe PMC text mining. Sharing a sentence is not in itself a finding about the gene and the disease. The quoted sentences say what the papers report.
lung carcinoma (9 papers, 2014 to 2023). "Previous work from our group has extensively characterised the role of LIMD1 as a tumour suppressor in lung cancer, therefore we investigated the potential of PF-477736 as a therapeutic option against LIMD1-deficient lung cancer cell lines." (PMID 34764236, 2021). "This biomarker signifies a new and exciting avenue for investigation in lung cancer biology and importantly a novel treatment strategy for LIMD1-deficient tumours." (PMID 34764236, 2021). "We have shown that it is possible to target these cells with a small molecule, allowing for the potential targeted treatment of a large proportion of lung cancer patients with LIMD1-deficient tumours." (PMID 34764236, 2021). "Human lung cancers deficient in LIMD1 expression represent 50% and 85% of LUAD and LUSC, respectively, and have been completely overlooked in preclinical studies." (PMID 34764236, 2021). "This is the first evidence supporting a targeted therapeutic approach for the treatment of lung cancers with reduced or loss of LIMD1 expression." (PMID 34764236, 2021). "LIMD1 (LIM domains containing 1) is a tumour suppressor gene encoded at the 3p.21.3 genomic locus, which is frequently ablated early in lung cancer development." (PMID 34764236, 2021). "This study provides proof-of-concept that LIMD1 expression can be used as a stratification marker for treatment, identifying a large group of lung cancer patients that could benefit from a targeted therapy against LIMD1 loss." (PMID 34764236, 2021). "In our study, LIMD1 overexpression in lung adenocarcinoma cells increased the sensitivity of lung adenocarcinoma cells to cisplatin, suggesting that LIMD1 is involved in regulating the susceptibility of lung cancer cells to this drug." (PMID 32754438, 2020). "LIM domain-containing protein 1 (LIMD1) is a tumor suppressor gene occasionally ablated early in lung cancer development." (PMID 36901953, 2023). "Studies have reported that LIMD1 expression is low in human lung cancer cells due to genetic or epigenetic modifications." (PMID 32754438, 2020). "Meanwhile, the survival prognosis analysis of LIMD1 in lung cancer from the Kaplan–Meier Plotter database also showed its significance in tumor inhibition." (PMID 33194664, 2020). "LIM domains‐containing 1 (LIMD1) is suggested as a tumor suppressor in lung cancer, but its mechanism in NSCLC remains elusive." (PMID 32239804, 2020). "In contrast, LIMD1 was reported to bind with the tumor suppressor Rb and repress E2F‐driven transcription to suppress cell proliferation in lung cancer." (PMID 30690883, 2019). "Loss of total gene expression is frequently observed, where reduced LIMD1 gene copy number and mRNA expression occur in a significant proportion of lung carcinomas." (PMID 29930174, 2018). "Recent studies have found that the decreased LIMD1 expression plays an important role in lung cancer progression; thus, LIMD1 may be an anticancer gene." (PMID 32754438, 2020). "Furthermore, LIMD1−/− mice develop increased numbers and larger volumes of lung adenomas following exposure to the carcinogen urethane or upon crossing with KRASG12D mice, highlighting loss of LIMD1 as a major driver in lung cancer and potential LUAD and LUSC susceptibility gene." (PMID 34764236, 2021). "Of note, this phenotype was validated in our isogenic pair of CRISPR-Cas9-generated LUAD A549 LIMD1+/+ and LIMD1−/− cells indicating this effect was not cell line specific and was relevant in the context of lung cancer biology." (PMID 34764236, 2021). "Taken together, our data open a new field of research into the aetiology, diagnosis and prognosis of LIMD1‐negative lung cancers." (PMID 29930174, 2018). "Our findings open a new field of research into the aetiology, diagnosis and prognosis of LIMD1‐negative lung cancers and hold the potential for advances in the stratification of patients with respect to deregulated HIF regulation and associated phenotypes." (PMID 29930174, 2018).
lung carcinoma (continued). "Expression of LIMD1 is absent or decreased in many cancers including breast cancer, lung carcinoma and blood cancers." (PMID 25207815, 2014). "Despite LIMD1’s key homoeostatic functions, the level of ablation in LUAD/LUSC and the large disease burden in lung cancer, there are currently no targeted therapies for LIMD1-deficient cancers." (PMID 34764236, 2021).
lung adenocarcinoma (6 papers, 2018 to 2023). A carcinoma that arises from the lung and is characterized by the presence of malignant glandular epithelial cells. "Recent evidence suggests that miR-550a-5p shows high expression and promotes tumor proliferation by binding to LIMD1 in lung adenocarcinoma." (PMID 36829221, 2023). "In conclusion, LIMD1 increases the sensitivity of lung adenocarcinoma cells to cisplatin via the GADD45α/p38 MAPK signaling pathway." (PMID 32754438, 2020). "In this study, we investigated the effect of LIMD1 on the sensitivity of lung adenocarcinoma cells to chemotherapy drugs and explored the mechanism(s) involved." (PMID 32754438, 2020). "In summary, a new potential prognostic and therapeutic biomarker, miR-550a-5p, has been identified by bioinformatics analysis and experimental validation in vitro and in vivo, which promotes lung adenocarcinoma by silencing a known suppressor oncogene LIMD1." (PMID 33194664, 2020). "This study investigated the role of LIMD1 in regulating the sensitivity of lung adenocarcinoma cells to cisplatin, and we also explored its mechanism of enhancing sensitivity." (PMID 32754438, 2020). "To further elucidate the mechanism by which LIMD1 increases the sensitivity of lung adenocarcinoma cells to cisplatin, we detected the expression of GADD45α and constituents of the p38 MAPK signaling pathway." (PMID 32754438, 2020). "In summary, LIMD1 increases the sensitivity of lung adenocarcinoma cells to cisplatin by activating the GADD45α/p38 MAPK signaling pathway." (PMID 32754438, 2020). "LIMD1 is a lung tumour suppressor, with decreased mRNA and protein expression shown to occur in a large proportion of lung adenocarcinomas." (PMID 29930174, 2018). "Our results indicate that LIMD1 expression level is significantly downregulated at both mRNA and protein levels in both lung adenocarcinoma (LUAD) and lung squamous cell carcinoma (LUSC), with a considerable contribution from its promoter methylation rather than its gene mutations." (PMID 33869018, 2021). "The observed increases in the sensitivity of lung adenocarcinoma cells to cisplatin may be due to LIMD1 regulation through the GADD45α/p38 MAPK signaling pathway." (PMID 32754438, 2020). "Similarly, siRNA-mediated inhibition of p38 MAPK expression also reversed the increase in the expression of proapoptotic proteins in lung adenocarcinoma cells induced by LIMD1 overexpression." (PMID 32754438, 2020). "Furthermore, we report that copy number variation at the LIMD1 locus occurs in 47.1% of lung adenocarcinoma patients, correlates with enhanced expression of a HIF target gene signature and is a negative prognostic indicator." (PMID 29930174, 2018). "Furthermore, in silico analysis of TCGA data shows that LIMD1 is lost in 47% of lung adenocarcinoma and serves as an independent prognostic marker." (PMID 29930174, 2018). "To further confirm whether the p38 MAPK signaling pathway is involved in the LIMD1-mediated increase in the sensitivity of lung adenocarcinoma cells to cisplatin, we either treated cells with SB203580 or transfected siRNA into cells to inhibit p38 MAPK signaling pathway activity." (PMID 32754438, 2020).
breast carcinoma (5 papers, 2010 to 2021). "LIMD1 protein expression has been previously shown to be significantly reduced or lost in human lung and breast cancers." (PMID 29930174, 2018). "In 2018, one study on the epigenetic regulation of LIM family genes in different breast cancer subtypes confirmed that the putative promoter region of LIMD1 and our predicted gene LPP may be abnormally methylated in the MDA-MB435 cell line." (PMID 31480430, 2019). "Cell-cycle-dependent phosphorylation of LIMD1 may play a role in breast cancer." (PMID 33869018, 2021).
COVID-19 (4 papers, 2021 to 2024). A disease caused by infection with severe acute respiratory syndrome coronavirus 2. "Therefore, the objective of our study is to investigate genetic variants in the genes AQP3, ARHGAP27, ELF5, IFNAR2, LIMD1, OAS1 and UPK1A, which were selected due to the association of these genes with the severity of COVID-19, in a sample of Amazonian indigenous peoples." (PMID 38543725, 2024). "Another study developed in 34 Spanish hospitals with 11,939 positive cases of COVID-19 identified the relationship of the AQP3, ARHGAP27, ELF5, IFNAR2, LIMD1, OAS1 and UPK1A genes with the severity of the disease." (PMID 38543725, 2024). "Seven new genes (AQP3, ARHGAP27, ELF5, IFNAR2, LIMD1, OAS1 and UPK1A) were related to the severity of COVID-19 in populations of European origin." (PMID 38543725, 2024).
cervical cancer (3 papers, 2020 to 2025). A primary or metastatic malignant neoplasm involving the cervix. "This article (“Deregulation of LIMD1-VHL-HIF-1α-VEGF pathway is associated with different stages of cervical cancer” DOI: 10.1042/BCJ20170649) is being retracted from the Biochemical Journal at the request of the Editor-in-Chief and the Editorial Board." (PMID 40457647, 2025). "LIMD1 acts as a scaffold protein to bind PHD2 and VHL, which degrade HIF by ubiquitination and increased methylation of LIMD1 and VHL are associated with upregulation of HIF1-α in cervical cancer." (PMID 34631530, 2021).
colorectal carcinoma (3 papers, 2014 to 2024). A malignant epithelial neoplasm that arises from the colon or rectum and invades through the muscularis mucosa into the submucosa. "Regarding LIMD1, it has been identified in colorectal cancer that its expression correlates with MDR, and it has also been established that its negative regulation can reverse drug resistance in multidrug-resistant cells of the same type of cancer." (PMID 38794149, 2024). "The role of LIM domain-containing protein 1 (LIMD1) in the multidrug resistance of colorectal carcinoma (CRC) has not yet been established." (PMID 25013501, 2014).
lymphoma (3 papers, 2014 to 2021). A malignant (clonal) proliferation of B- lymphocytes or T- lymphocytes which involves the lymph nodes, bone marrow and/or extranodal sites. "Using high throughput expression profiling, we have previously identified LIMD1 as a common marker associated with the oncogenic transcription factor IRF4 in EBV-related lymphomas and other hematological malignancies." (PMID 29464072, 2018). "We further show here that the LIMD1 protein level is associated with NFκB activity (as indicated by IκBα phosphorylation), in B and T lymphoma cell lines." (PMID 29464072, 2018). "Thus, we believe that LIMD1 plays an oncogenic role in EBV-associated lymphomas and other hematological malignancies, although further verification in animal models is required." (PMID 29464072, 2018). "Our GEO high throughput profiling has revealed that LIMD1 is associated with IRF4 expression in B-cell lymphomas, including EBV-associated lymphomas and DLBC." (PMID 33869018, 2021). "Our previous study has shown that LIMD1 and IRF4 expression levels positively correlate in different hematological malignancies, including EBV-associated lymphomas." (PMID 29464072, 2018). "We confirmed the correlation of IRF4 with LIMD1 and CFLAR in a panel of cell lines derived from lymphomas." (PMID 25207815, 2014).
B-cell Lymphoma (2 papers, 2014 to 2021). "A pool of important genes involved in B-cell development, oncogenesis, cell cycle regulation, and cell death including BATF, LIMD1, CFLAR, PIM2, and CCND2 are common signatures associated with IRF4 in non-Hodgkin B cell lymphomas." (PMID 25207815, 2014).
gastric cancer (2 papers, 2020 to 2021). A primary or metastatic malignant neoplasm involving the stomach. "These plots suggest Zyxin, LPP, LIMD1, TRIP6, and FBLIM display high levels of mutational frequency in stomach cancer." (PMID 33808029, 2021).
head and neck cancer (2 papers, 2010 to 2021). A primary or metastatic malignant neoplasm affecting the head and neck. "Targeting such cancers is particularly attractive as LIMD1 loss has been further observed in breast, cervical, gastric, renal, and head and neck cancers." (PMID 34764236, 2021).
non-Hodgkin lymphoma (2 papers, 2014 to 2021). Distinct from Hodgkin lymphoma both morphologically and biologically, non-Hodgkin lymphoma (NHL) is characterized by the absence of Reed-Sternberg cells, can occur at any age, and usually presents as a localized or generalized lymphadenopathy associated with fever and weight loss. "We have verified LIMD1 and CFLAR as two novel genes whose expression is correlated with IRF4 in non-Hodgkin lymphomas, and shown that CFLAR is likely an IRF4 target." (PMID 25207815, 2014).
brain tumors (1 paper, 2024). "Through a comparative analysis of the different histologies of brain tumors, we detected that LIMD1 was significantly more regulated in GB than other brain tumors." (PMID 38794149, 2024). "The function of LIMD1 has not yet been characterized in brain tumors, but we detected that overexpression of this marker is associated with a poor prognosis of the disease." (PMID 38794149, 2024).
cardiac hypertrophy (1 paper, 2025). "This research elucidates the regulatory dynamics and mechanisms of LIMD1 under pathological conditions, suggesting its potential as a therapeutic target for pathological cardiac hypertrophy." (PMID 39937832, 2025). "We discovered that overexpression of LIMD1 attenuates this signaling, thus mitigating pathological cardiac hypertrophy." (PMID 39937832, 2025). "We further investigated the effects of LIMD1 overexpression on TAC-induced cardiac hypertrophy and fibrosis." (PMID 39937832, 2025). "Overexpression of LIMD1 was able to reverse excessive cardiac hypertrophy and fibrosis in HF mice, as well as improve cardiac function." (PMID 39937832, 2025). "In this study, we observed a significant upregulation of LIMD1 expression in hypertrophic cardiomyocytes, and found that overexpression of LIMD1 mitigated the progression of cardiac hypertrophy." (PMID 39937832, 2025). "To investigate the role of LIMD1 in cardiac hypertrophy, we analyzed its protein expression under conditions of hypertrophy." (PMID 39937832, 2025). "Moreover, gain-of-function studies have clarified the protective role of LIMD1 in inhibiting the progression of pathological cardiac hypertrophy." (PMID 39937832, 2025). "Therefore, our findings suggest that LIMD1 improves outcomes in post-HF pathological cardiac hypertrophy by targeting the YAP1/AKT/GSK3β signaling pathway." (PMID 39937832, 2025). "Firstly, employing cardiac-specific LIMD1 overexpression or knockout models could provide deeper insights into its protective role against pathological cardiac hypertrophy." (PMID 39937832, 2025). "However, the role of LIMD1 in pathological cardiac hypertrophy remains poorly understood." (PMID 39937832, 2025). "Mechanistically, both in vivo and in vitro experiments demonstrated that overexpression of LIMD1 significantly inhibits the activation of the YAP1/AKT/GSK3β signaling pathway, thereby reversing pathological cardiac hypertrophy induced by pressure overload." (PMID 39937832, 2025). "Remarkably, all these changes indicative of cardiac hypertrophy and fibrosis induced by TAC were significantly reversed by overexpressing LIMD1." (PMID 39937832, 2025).
cholangiocarcinoma (1 paper, 2021). A carcinoma that arises from the intrahepatic biliary tree (intrahepatic cholangiocarcinoma) or from the junction, or adjacent to the junction, of the right and left hepatic ducts (hilar cholangiocarcinoma). "Mutation analysis of TCGA dataset in TIMER, cBioportal, and DriverDBv3 portals shows that the Limd1 gene undergoes low rates of mutation in NSCLC (4/485 in LUSC and 4/517 in LUAD), but undergoes higher rates in DLBC (2/37), UCEC (16/531), and cholangiocarcinoma (CHOL, 1/36)." (PMID 33869018, 2021).